IFNG (interferon gamma)
Diseases named in the same sentence as IFNG in open-access papers (continued):
Sharing a sentence is not in itself a finding about the gene and the disease.
type 1 diabetes (continued). "The modified cells were then exposed to proinflammatory cytokines mimicking the pathogenic inflammatory beta cell microenvironment of pancreatic islet in type 1 diabetes, i.e. IFNγ/IL1β or IFNγ/IL1β/TNFα and analysed for endogenous XBP1 splicing by qPCR or light emission in cell lysates." (PMID 30532033, 2018). "As Il-1β, IFNγ and TNFα are important cytokine effectors of β-cell death in type 1 diabetes, we next sought to determine whether Myt3 is reduced by immune-cell attack in non-obese diabetic (NOD) mice." (PMID 23236509, 2012). "We treated isolated B cells with IFNγ for 5 days, and found increased CXCR3 expression compared with unstimulated cultures in ND donors and individuals with type 1 diabetes, whether RO or LD." (PMID 41273416, 2026). "Overall, our study shows that the reduced expression observed on antigen-experienced B cells in type 1 diabetes is not due to a failure to mount a response to IFNγ or different isoform expression." (PMID 41273416, 2026). "IFNγ increased DN (IgD−CD27−) B cells in samples from ND individuals, with a reciprocal decrease in naive B cells, but this was less apparent in samples from donors with type 1 diabetes." (PMID 41273416, 2026). "Type 1 diabetes is an autoimmune disorder, in which auto-reactive T-cells (CD4 and CD8) produce pro-inflammatory cytokines such as TNF and IFNγ, which are able to mediate pancreatic beta cell death and activate macrophages, leading to further cytokine production and increased beta cell destruction." (PMID 37762318, 2023). "Using high-throughput RNA sequencing data from human islets and EndoC-βH1 cells exposed to IFNα or IFNγ/IL1β, we evaluated the role of ADAR1 in human pancreatic β cells and determined the impact of the type 1 diabetes pathophysiological environment on ADAR1-dependent RNA editing." (PMID 36518246, 2022). "While IFNγ is generally thought to be important in the development of type 1 diabetes, in the NOD model, the lack of IFNγ or IFNγ receptor does not prevent the development of disease." (PMID 34478449, 2021). "Significant normalised enrichment scores were amongst others found in the Graft-versus-host disease pathway, Allograft rejection pathway, Type I diabetes mellitus pathway and Antigen processing and presentation in all of which MHC class I and II, as well as IFNγ have been implemented." (PMID 31853095, 2019). "These epigenetic modifications are aberrant in the nonobese diabetic mouse model of insulin-dependent diabetes, resulting in Th0 cells that spontaneously express IFNγ." (PMID 31238969, 2019). "In Type 1 diabetes patients treated with teplizumab, responders showed a population of CD8 memory T cells that expressed EOMES and inhibitory receptors and retained some effector function as shown by IFNG and GZB expression, like the DP T cells in this study." (PMID 30534127, 2018). "However, in patients with type 1 diabetes, CD24hiCD38hi B cells failed to reduce IFNγ, TNFα and IL-17 production from CD4+ T cells." (PMID 34616408, 2021). "As TYK2 inhibition has raised as a potential therapeutic target for the prevention or treatment of type 1 diabetes, we investigated whether the selective TYK2 inhibitor deucravacitinib could protect β-cells from the effects of IFNα and other proinflammatory cytokines (i.e., IFNγ and IL-1β)." (PMID 37854597, 2023). "In this study we show that IFNα and IFNγ differentially regulate the proteasomal composition of beta cells and demonstrate that INS-DRiP peptide recognition may be involved in later phases of type 1 diabetes pathogenesis as an amplificatory phenomenon of beta cell destruction." (PMID 37581620, 2023).
prostate carcinoma (129 papers, 2003 to 2026). A carcinoma that arises from epithelial cells of the prostate gland. "This pro-survival role is shared with IL-12, whose depletion by antibodies causes prostate cancer cell death via IFNγ in vivo." (PMID 30158439, 2018). "In particular, loss of responsiveness to IFNγ has previously been linked to prostate cancer progression." (PMID 17280610, 2007). "We next examined the correlation between expression of UBA1 and IFNG or CD8+ T cell–related signatures in cancer types other than prostate cancer." (PMID 39540840, 2025). "Meanwhile, it was also proposed that the inhibitory functional of CD8+T cell-intrinsic AR pathway was suppressed directly by IFNG in prostate cancer immunotherapy." (PMID 38491510, 2024). "The enhanced stability of IFNGR1 leads to stimulation of the type II interferon-gamma (IFN-γ) inflammatory reaction pathway in prostate carcinomas." (PMID 35814468, 2022). "We further identified that the expression of IFNG was negatively correlated with RSI in all cancer sites except for prostate cancer in MMD." (PMID 34078917, 2021). "Decreased numbers of circulating iNKT have been found in multiple tumor types such as advanced prostate cancer and are accompanied by decreased IFNγ production and increased IL-4 production by iNKT." (PMID 30298063, 2018). "We demonstrated DNA demethylation of the promoter sequences of selected antigen-presenting machinery genes (TAP-1/LMP-2, TAP-2) upon IFNγ treatment both in the MHC class I-deficient tumour cell line TC-1/A9 and in the prostate cancer cell line TRAMP-C2." (PMID 25071011, 2014). "Fn14 expression was up-regulated in PC-3 human prostate cancer cells in presence of inflammatory cytokines (TNFα/IFNγ) as well as in presence of bovine fetal serum." (PMID 23077618, 2012). "IFNγ has been shown to be capable of bestowing increased sensitivity to Fas-mediated cell death in prostate cancer cells." (PMID 23056548, 2012). "In prostate cancer cells it has been reported that IFNγ apoptotic effects are promoted by p21 stimulation, which inhibits G1 and S phase of cell cycle." (PMID 17697357, 2007). "However, a pro-metastatic role of IFNG has also been observed in prostate cancer cells, where it promotes EMT through the activation of Janus kinase/signal transducer and activator of transcription 1 signaling." (PMID 38287309, 2024). "Nonetheless, we found divergent results in prostate cancers wherein B7-H3–high tumors displayed negative enrichment of Hallmark IFNγ, IFNα, and TNFα response gene sets." (PMID 38709075, 2024). "It has been also suggested that AR inhibition may improve immune checkpoint blockade effectiveness in models of prostate cancer via increased interferon-gamma expression in CD8 + T cells." (PMID 38167882, 2024). "In the same study, we reported that through the alteration of cell culture conditions using hormone-enriched media, the expression of class II could be increased, similar to the results seen when prostate cancer cells are induced with interferon gamma (IFN-γ)." (PMID 36499557, 2022). "To examine whether fucoidans can activate PBMCs and support the killing of prostate cancer cells, we looked at changes in the IFNγ released level for the immune/tumor co-culture." (PMID 35049864, 2021). "We have previously demonstrated in mice that PD-L1 expression increases on tumors following immunization, and that PD-L1 expression increases on circulating prostate cancer cells shortly after vaccination in patients with prostate cancer who developed PAP-specific IFNγ-secreting T cells." (PMID 29876010, 2018). "Interestingly, this aberrant iNKT activation was reversible by the simultaneous addition of αGalCer and IL-12, which allowed iNKT cells to produce IFNγ in response to these CD1d-expressing prostate cancer cells." (PMID 30298063, 2018).
prostate carcinoma (continued). "Among these, miR-221 was recently reported and externally validated as an independent predictor of cancer-related death of high-risk prostate cancer patients, by partially regulating JAK/STAT signaling pathway and sensitizing prostate cancer cells to interferon-gamma treatment [17•]." (PMID 26267226, 2015). "However, an MVA-MUC-1 vaccine induced an IFNγ+ T-cell response to MUC-1 after short-term culture in 7/34 patients with prostate cancer." (PMID 22729556, 2012). "For instance, positive enrichment of Hallmark IFNγ, IFNα, and angiogenesis gene sets and negative enrichment of Hallmark inflammatory response gene sets were uniquely observed in B7-H3–high metastatic prostate cancers." (PMID 38709075, 2024). "Importantly, the effects of BAY1082439 on inhibition of cell proliferation and PI3K, IFNα and IFNγ pathways could be observed 24–48 h after a bullet dose on the Pten-null prostate cancer model in vivo without influence AR expression levels." (PMID 35013322, 2022). "However, based on the increased numbers of Tbet+Th1 cells in TLO from patients with evanescent prostate carcinoma, we expected that IFNγ, produced by Th1-cells, stimulates local production of CXCL10—a chemokine that attracts effector lymphocytes to inflammatory sites." (PMID 28567040, 2017). "Here, we show that IFNγ treatment induced expression of major histocompatibility class-I (MHC-I) genes and PD-L1 in prostate cancer cells in vitro." (PMID 35459800, 2022). "In prostate cancer, epigenetic silencing of the crucial component JAK1 kinase of the IFNγ signaling pathway led to IFNγ-insensitivity-mediated tumor evasion and resistance to immunotherapy." (PMID 33406696, 2021). "The murine prostate cancer cells (RM-1) mixing with MSCs treated with tumor necrosis factor alpha (TNF-α) and interferon gamma (IFN-γ) or vehicle were subcutaneously injected into C57 mice." (PMID 29268703, 2017). "In line with this, we have previously shown that AE37 vaccination offered a clinical benefit in prostate cancer patients, with high levels of preexisting immunity to the native AE36 peptide detected by IFNγ ELISPOT." (PMID 27891225, 2016). "We aimed to investigate the effects of a 6-month HOET on interleukin (IL)−1 beta (IL-1ß), IL-2, IL-6, IL-10, IL-12p70, tumor necrosis factor-alpha (TNF-α), interferon-gamma (IFN-γ), and the mGPS of colorectal, breast, and prostate cancer patients after surgery." (PMID 40498221, 2025). "Interestingly, it has been reported that NK cells exposed to cancer cells (glioblastoma and prostate cancer) downregulate TIM-3 expression, which correlates with decreased cytotoxicity and lower interferon gamma production." (PMID 41051510, 2025). "Interferon gamma (IFNγ), interferon alpha (IFNα), and interleukin 6 (IL6)-Janus kinase (JAK)-signal transducer and activator of transcription 3 (STAT3) signaling were assessed in enzalutamide-sensitive and -resistant prostate cancer cells." (PMID 41097714, 2025). "We find upregulation of TIGIT—a marker of T cell exhaustion during masculinizing GAHT—in vivo, but we also find induction of TNF responses and IFNγ responses by NK cells, which seems at odds with reported impairments of TH1 responses in male prostate cancer patients." (PMID 39232147, 2024). "Moreover, prostate cancer tissues and cell lines with decreased GALNT7 expression exhibited significant enrichment of immune-related pathways, such as immunoregulatory interaction and IFNγ response." (PMID 40824763, 2025). "Prostate cancer treatment does not appear to alter MAIT cell numbers but decreases proliferation and immune cell IFNγ production." (PMID 37325799, 2023). "We also generated derivatives of 22Rv1 prostate cancer cells (which overexpress CDK19 relative to CDK8) with the knockout of CDK8 and CDK19, individually and in combination (dKO), and analyzed STAT1 S727 phosphorylation with and without IFNγ treatment." (PMID 37378433, 2023).
glioblastoma (127 papers, 2002 to 2026). The most malignant astrocytic tumor (WHO grade IV). "The cytokines IL-1Ra, IL-13, and IFNγ showed poor diagnostic usefulness for prognosis in glioblastoma patients even though their concentrations changed significantly." (PMID 38003396, 2023). "Studies have shown that upregulation of the canonical interferon-gamma signaling pathway is associated with glioblastoma progression, and its expression in the tumor microenvironment significantly impacts overall survival in pediatric diffuse midline glioma (DMG) patients." (PMID 40842996, 2025). "These are the IFNG pathway in the glioblastoma analysis, the allograft rejection in the T cells of monkeys, and the genes downregulated by UV in T cells of human SARS-CoV-2 patients." (PMID 38981682, 2024). "Another study recently reported that the IFNγ from CD4+ T cells in the solid tumor microenvironment drives microglial phagocytosis of glioblastoma cells." (PMID 38893085, 2024). "Here, we report the first high throughput transcriptomic analysis of the model human glioblastoma cell line, U-87MG, treated with HeberFERON, IFNα2b and IFNγ for 72 h." (PMID 37644431, 2023). "Second, we searched for the appearance of W>F substitutants in the immunopeptidome of the glioblastoma cell line RA, in which we previously detected their enrichment in the proteome following IFNγ treatment." (PMID 35264796, 2022). "Decreased expression on healthy human NK cells upon exposure to glioblastoma cell lines, corresponding with decreased cytotoxicity and IFNγ production." (PMID 34594338, 2021). "Interferon-γ (IFNγ), tumor necrosis factor-α (TNFα), granzyme B, and IL-4 levels were significantly increased in iNKT cells stimulated with the α-GalCer-pulsed glioblastoma cell lines in a CD1d-dependent manner." (PMID 33128583, 2021). "CAR NK cells exhibited GSC and differentiated glioblastoma cell cytotoxicity increased levels of interferon-gamma (IFN-γ), and prolonged survival of glioblastoma-bearing mice in preclinical studies." (PMID 33572835, 2021). "Conversely, data have also shown that IFNγ enhances viral replication in placental and glioblastoma cells." (PMID 33378361, 2020). "Together, these results indicate that IDO expression above a certain level can inhibit virus replication in glioblastoma cells, but also that the majority of IFNγ-induced inhibition of virus replication occurs via a different pathway." (PMID 22924042, 2012). "We used the small molecule inhibitor of IDO activity, 1-methyl-tryptophan (1-MT), to assess the role of IDO in the observed reduction in virus yields from glioblastoma cells treated with IFNγ prior to low-MOI infection." (PMID 22924042, 2012). "Both wild-type KOS virus and JD0G were moderately sensitive to IFNγ at low MOI in glioblastoma cells, an effect that was dramatically reduced at higher MOI." (PMID 22924042, 2012). "In this report, we characterized an ICP0-deficient oHSV vector, JD0G, for its ability to replicate in glioblastoma cells in the absence and presence of IFNγ." (PMID 22924042, 2012). "We observed that IFNγ treatment of human glioblastoma cells induced the expression of IDO and that this expression was quelled by infection with both wild-type and JD0G viruses." (PMID 22924042, 2012). "In order to determine if the glioblastoma cells used in this study produce active IDO protein either constitutively or in response to IFNγ, IDO-enzymatic activity was assessed by measuring the level of kynurenine in the supernatants of IFNγ-treated cells." (PMID 22924042, 2012). "Importantly, those CAR-T cells exhibited the elevated expression of interferon-gamma (IFN-γ) and improved migration capacity through the stromal ECM that were associated with the achieved positive effect toward glioblastoma xenografts." (PMID 39996879, 2025).
glioblastoma (continued). "This suggests that in glioblastoma patients, these cells lack the ability to be fully activated when primed, as evidenced by the reduced levels of IFNγ and CD69, which allows speculation that these cells may be terminally exhausted." (PMID 39513882, 2024). "In summary, single-cell RNA-sequencing data from human ND and R glioblastomas showed an accumulation of NK cells with reduced expression of activation, interferon-gamma and cell cycle genes and enhanced expression LTB and apoptosis-associated genes, suggesting an exhausted NK cell phenotype." (PMID 36230839, 2022). "We found that TAM, monocyte, pre-dendritic cell (DC), migratory DC, pDC, and T-cell populations were enriched in CD73hi versus CD73lo glioblastoma, as were inflammatory signatures for IFNγ and MHC-I signaling and signatures of Immunoscore, T cell inflammation, and cytolytic activity (CYT)." (PMID 35973991, 2022). "Exploring the role of IFNG in glioblastoma (GBM) may optimize the current treatment paradigm of this disease." (PMID 34566988, 2021). "However, we observed marked differences between the glioblastoma cell lines in both the IFNγ sensitivity of virus replication and the involvement of IDO activity in the inhibition of virus replication." (PMID 22924042, 2012). "Moreover, while glioblastoma cell lines produced IDO protein when stimulated with IFNγ, IDO induction had a minimal effect on virus replication." (PMID 22924042, 2012). "Likewise, Clinica Universidad de Navarra conducted a Phase 1b, randomized, multicenter, open-label study (TARGET-I, NCT02197169) from 2014 to 2018, investigating conditional replicative adenovirus (DNX-2401) and interferon gamma (IFN-γ) for recurrent glioblastoma." (PMID 38022620, 2023). "Based on preclinical models, it has been suggested that CAR-T cells, in addition to targeting cancer cells, may also activate the host immune system, and the possible role of an in vivo production of interferon-gamma (IFNγ) has also been hypothesized in a syngeneic mouse glioblastoma model." (PMID 37173879, 2023). "We examined the percentage of TIM-3 positivity and the activation status (via CD69 and IFNγ) following the PMA and ionomycin stimulation of glioblastoma patients’ T and NK cells compared to those of healthy individuals." (PMID 39513882, 2024). "IFNγ positivity was significantly increased when CD4+ and CD8+ T cells and NK cells from healthy donors and glioblastoma patients were stimulated with PMA and ionomycin." (PMID 39513882, 2024). "These pro-inhibitory changes are also correlated with reduced levels of the activation marker CD69 and the pro-inflammatory cytokine IFNγ in CD4+ and CD8+ T cells, as well as NK cells from glioblastoma patients." (PMID 39513882, 2024). "Subsequent reductions in the positivity of the cell activation marker CD69 and the key pro-inflammatory cytokine IFNγ were also observed in CD4+ and CD8+ T cells and NK cells from glioblastoma patients." (PMID 39513882, 2024). "Regarding its function, TCC88 showed in vitro cytotoxicity against an autologous glioblastoma cell line and a multifunctional pro-inflammatory phenotype with strong secretion of TNF, IFNγ, granzyme B, GM-CSF and others." (PMID 37198490, 2023). "The authors found that intratumoral interferon gamma (IFN-γ) and granzyme B (GzmB) were decreased, with decreased numbers of CD8+ TILs, providing evidence for the role of abnormal phospholipid synthesis in glioblastoma immunosuppression." (PMID 34222022, 2021). "We conducted expression profiling of CD274 (PD-L1), GATA3, IFNG, IL12R, IL12RB2, IL4, PDCD1 (PD-1), PDCD1LG2 (PD-L2), and TBX21 (T-bet) using data of 158 glioblastoma multiforme (GBM) patients with clinical information available at The Cancer Genome Atlas." (PMID 29721184, 2018).